IL6 (interleukin 6)
Diseases named in the same sentence as IL6 in open-access papers (continued):
Sharing a sentence is not in itself a finding about the gene and the disease.
Insulin resistance (continued). "A large amount of IL-6 in a high-glucose environment can reduce insulin sensitivity, and excessive TNF-α will cause an increase in the free fatty acid content, which will eventually lead to insulin resistance." (PMID 35327635, 2022). "Elevated concentrations of TNF-α, IL-1b, IL-6 and leptin may also worsen insulin resistance and increase fetal overgrowth." (PMID 35957820, 2022). "Thus, the conclusion is that IL-6 is one of the essential adipokines that directly increase insulin resistance in adipocytes." (PMID 36364860, 2022). "Taken together, our findings suggested that the uptake of H-Exo by liver macrophages may result in macrophage activation and subsequent release of TNF-α and IL-6, thus contributing to the development of insulin resistance." (PMID 33431899, 2021). "In this context, circulating IL-6, clusterin and irisin may represent possible therapeutic targets for insulin resistance in obese subjects." (PMID 33905632, 2021). "In addition, it has been suggested that IL-6 is involved in insulin resistance and its complications." (PMID 34149621, 2021). "Smaller adipocytes retain their insulin sensitivity, while hypertrophied adipocytes are likely to become insulin resistant and secrete proinflammatory cytokines, such as tumor necrosis factor-alpha (TNFα) and interleukin 6 (IL-6), which can also induce insulin resistance in other tissues." (PMID 33671850, 2021). "Furthermore, a positive correlation was found between miRNA-122 expression and TNF-α (r = 0.82), IL-6 (r = 0.83) and insulin resistance (r = 0.8)." (PMID 34077450, 2021). "IL-6 level is elevated in patients with lipid abnormalities and insulin resistance." (PMID 34831450, 2021). "However, in some of the included studies that did not measure HbA1c levels, other positive changes in systemic parameters such as interleukin (IL)-6 levels, high-sensitive C-reactive protein levels, insulin, and insulin resistance were obtained." (PMID 34439554, 2021). "Moreover, in a rat model of insulin resistance, a reduction in the pro-inflammatory cytokine IL-6 circulating levels was observed after Myo supplementation." (PMID 34199095, 2021). "Besides, data regarding insulin resistance, interleukin 6 (IL-6), tumor necrosis factor-α (TNF-α), and other inflammatory markers were lacking in our study." (PMID 34740348, 2021). "Some clinical studies have shown that IL-6 is needed to reduce visceral adipose tissue during exercise, which in turn may lead to improved insulin resistance." (PMID 34884703, 2021). "Interestingly, IL-6, IL-1, and TNF-α, which have been associated with insulin resistance and atherosclerosis, are also among the cytokines which play a role in the pathogenesis of vitiligo, possibly highlighting a link between these two conditions." (PMID 34445526, 2021). "hydroalcoholic extract decreased blood glucose, insulin resistance, leptin and IL-6 levels, lipid profile, and vascular dysfunction, while increasing the expression of insulin signaling proteins in skeletal muscle, adipose tissue and plasma glucagon like peptide-1 (GLP-1) levels." (PMID 33435282, 2021). "In addition, IL‐6 is considered to be involved in the development of inflammation, insulin resistance, as well as β‐cell dysfunction." (PMID 33960655, 2021). "Indeed, both ingredients have demonstrated its ability to decrease the circulating levels of IL-6 in old rats as well as the gene expression of several inflammatory and oxidative stress markers in metabolic tissues contributing to reduced insulin resistance." (PMID 34356299, 2021). "Given the well-established link between IL-6 and insulin resistance, this suggests that IL-6 may be an EGT target for preventing insulin resistance in skeletal muscle." (PMID 33806754, 2021). "IL-6 is thought to increase insulin resistance through its inhibition of cytokine signalling." (PMID 34813621, 2021).
Insulin resistance (continued). "Thus, the selectively blocking of IL-6 trans signaling is needed to prevent the pro-inflammatory effects of IL-6 signaling and develop drugs for inflammation-induced insulin resistance." (PMID 34576181, 2021). "In addition, high levels of endotoxemia have been shown to increase levels of TNF-α, IL-6, and insulin resistance." (PMID 34073366, 2021). "Furthermore, the obesity-related exosomes homed the macrophage to the liver and adipose tissues, in which macrophages secreted TNF-α and IL-6 to result in insulin resistance." (PMID 33816504, 2021). "During the past two and a half decades, factors such as physical inactivity, insulin resistance, increased plasma levels of IL-6, increased intramuscular fat storage, and adequacy of protein consumption have been identified as “therapeutic targets” in combating sarcopenia during the aging process." (PMID 35010928, 2021). "IL-6 and CRP are associated with hyperglycemia and insulin resistance." (PMID 33530554, 2021). "In addition, TNF-α increases circulating levels of leptin and resistin when interacting synergistically with IL-6, favoring increased peripheral insulin resistance and greater chances of developing T2DM." (PMID 33520042, 2021). "In addition, osteoporosis and sarcopenia shared common underlying mechanisms, including insulin resistance, decreased anabolic hormones, such as IGF-1 and testosterone, increased inflammatory cytokines, including IL-1, IL-6, and TNF-α, as well as dysbiosis." (PMID 33807573, 2021). "Furthermore, TNF-α and IL-6 concentrations are generally related to insulin levels; in fact, these cytokines play an important role in the pathogenesis of insulin resistance." (PMID 33530512, 2021). "Studies have shown that there is an association of inflammation with diabetes where there is an increase in the circulating levels of inflammatory markers, including C reactive protein (CRP), interleukin-6 (IL-6), and fibrinogen, which lead to insulin resistance." (PMID 33440707, 2021). "IL-6, up to 30% of which is produced by adipose tissue, negatively regulates insulin signalling and glucose metabolism in adipocytes, and promotes insulin resistance in liver cells." (PMID 34658643, 2021). "Although, chronic inflammation remains the main mechanism triggers insulin resistance, adipose tissue produces both pro- and anti-inflammatory substances including IL-6, clusterin and irisin which may play a role in glucose hemostasis." (PMID 33905632, 2021). "Some studies have shown that IL-6 plasma concentrations may be positively correlated with systemic insulin resistance, IL-6 liver expression, hepatic inflammation, and fibrosis degree in NAFLD patients." (PMID 34447378, 2021). "In addition, this interaction has been associated to elevated IL-6 serum levels in the same study upon CPEB1 knock-out mice; this finding is known to be correlated to insulin resistance and even cancer (Fève and Bastard, 2009)." (PMID 34912244, 2021). "Insulin resistance is associated with an increase of TNF-α, IL-1α, IL-1β, IL-6, and leptin." (PMID 34970568, 2021). "Intermittent hypoxia could lead to glucose intolerance and insulin resistance by promoting the release of pro-inflammatory cytokines, such as interleukin-6 and tumor necrosis factor." (PMID 34393806, 2021). "However, plasma IL-6 levels are rapidly elevated during exercise, and exercise is an effective way to alleviate insulin resistance." (PMID 34943061, 2021). "Experiments have confirmed that the high expression of IL-6 in PCOS may play a role in the pathogenesis of PCOS through the synergistic effect of insulin resistance and chronic inflammation." (PMID 34457027, 2021). "Additionally, oxidative stress induces insulin resistance of adipocytes and increases secretion of several cytokines and pro-inflammatory interleukins, IL-6 and TNF-α by adipocytes." (PMID 34439481, 2021).
Insulin resistance (continued). "In addition, clinical studies have shown that sleep deprivation increases levels of Interleukin 6 (IL-6) and C-reactive protein (CRP), both of which have been linked to MetS constituents through increased insulin resistance." (PMID 34670597, 2021). "Nonetheless, it is possible that IL-6 and IL-6 receptor (IL-6R) signaling in adipose tissue-resident macrophages may induce clinical inflammation and mediate insulin resistance." (PMID 34576181, 2021). "Of these cytokines, interleukin 6 (IL-6) has been reported to induce hepatic insulin resistance." (PMID 34445261, 2021). "Arterial hypertension, dyslipidemia, older age, sedentary lifestyle, and abdominal obesity are key risk factors for T2DM since the adipose tissue secretes several biomarkers, such as resistin, TNF-α, and IL-6, which can induce a chronic inflammatory state and insulin resistance." (PMID 34012421, 2021). "In general, a hypercaloric diet that was high in protein, fat, and sodium and deficient in vitamins, mainly fat-soluble, was associated with a lower concentration of adiponectin and a higher concentration of IL-6, which favor the presence of metabolic risks, including insulin resistance." (PMID 35010709, 2021). "In NAFLD, IL-6 may enhance hepatic repair and regeneration; however, IL-6 may also promote insulin resistance and hepatocyte apoptosis, thus contributing to NASH development." (PMID 33766130, 2021). "Conversely, negative correlations were observed between miRNA-126-3p and miRNA-146a levels and TNF-α (r = -0.7 and r = -0.82 respectively), IL-6 (r = -0.65 and r = -0.78 respectively) as well as insulin resistance (r = -0.67 and r = -0.78 respectively) (all p<0.05)." (PMID 34077450, 2021). "Such insulin resistance was associated with modest, not statistically significantly higher expression of canonical markers of low-grade inflammation, namely IL-6 and TNFα, in adipose tissue and liver." (PMID 33819308, 2021). "IL-6 has a role in the development of insulin resistance and hyperglycemia." (PMID 33530554, 2021). "Additionally, we examined the relationship between miRNA levels and plasma concentrations of inflammatory factors including tumor necrosis factor alpha (TNF-α) and interleukin 6 (Il-6) as well as insulin resistance." (PMID 34077450, 2021). "Also, increased levels of TNF-α and IL-6 along with other proinflammatory cytokines were found in obese children and adolescents with insulin resistance and/or T2DM." (PMID 34344352, 2021). "Since IL-6 may regulate peripheral insulin resistance, it was hypothesized that blockade of the IL-6 pathway with tocilizumab would result in improved insulin sensitivity." (PMID 34747368, 2021). "Circulating IL-6, clusterin and irisin may represent possible therapeutic targets for insulin resistance in obese subjects." (PMID 33905632, 2021). "Moreover, similar effects on the decrease of insulin resistance were shown in RA patients treated with IL-6 antagonists, anti-IL-1 agents or T-cell costimulation blockade." (PMID 33995414, 2021). "High IL-10 levels may also increase insulin sensitivity by ameliorating the inflammatory responses to TNF-α and IL-6, which contribute to insulin resistance in PCOS." (PMID 34233746, 2021). "Increasing levels of inflammatory cytokines specially TNF-α are at the heart of inflammatory cascades linked to insulin resistance, as we observed in present study in which levels of TNF-α and IL-6 were significantly higher in diabetic and pre-diabetic patients compared to healthy controls." (PMID 34077450, 2021). "Moreover, studies conducted on overweight women have shown a direct positive correlation between insulin resistance and circulating IL-6 levels." (PMID 33322719, 2020). "Secretion of adipokines (e.g. leptin) and cytokines (e.g. TNF-α, IL-6 and IL-1β), oxidative stress and, possibly, the gut microbiome contribute to pregnancy-induced insulin resistance, although understanding of pregnancy-induced insulin resistance is incomplete." (PMID 32556615, 2020).
Insulin resistance (continued). "Moreover, vitamin is a negative modulator of inflammatory cytokine such as TNF-α and IL6, which are closely related to insulin resistance." (PMID 33042976, 2020). "The altered adipokines and pro-inflammatory cytokines such as IL-6, TNF-α, and MCP-1 which secreted from adipose tissue may directly or indirectly caused insulin resistance through impairing insulin signaling or activating pro-inflammatory pathways." (PMID 32265835, 2020). "Local alterations in IL-6 paracrine signalling originating in adipocytes might then explain at least a portion of the localized insulin resistance of the A-Nicastrin mice." (PMID 32603641, 2020). "In addition, previous studies have revealed that NF-κB and its target inflammatory factor genes such as IL-1 and IL-6 played a key role in the development of insulin resistance and T2DM." (PMID 33240215, 2020). "Similarly, female Sprague-Dawley rats and female BALB/c mice, after 8 weeks of treatment (10 mg/kg/day), exhibited a significant increase in TNF-α, IL-6, IL-1β, and IL-8 levels, in addition to insulin resistance." (PMID 32373066, 2020). "IL6 has also been shown under some circumstances to stimulate insulin secretion, whilst subsets of islet macrophages have been reported to simultaneously impair insulin secretion but promote beta-cell proliferation in models of insulin resistance." (PMID 32599074, 2020). "Correlations of IL-6, leptin and TNF-α with diabetes have been explored extensively, and most of these studies obtained results similar to ours that TNF-α, IL-6 and leptin were positively associated with insulin resistance or secretion." (PMID 33292292, 2020). "Interleukin 6 (IL-6) is a multipotent cytokine that mediates inflammatory response by controlling cell differentiation, migration, proliferation and apoptosis, thus playing a role in the development of insulin resistance." (PMID 32785222, 2020). "Exercise suppresses the production of TNFα, which is known to cause insulin resistance through skeletal muscle IL-6 secretion without weight loss while inducing secretion of anti-inflammatory cytokines to improve systemic inflammation." (PMID 32954935, 2020). "Interleukin 6 is another cytokine that appears to be involved in inducing insulin resistance." (PMID 33322719, 2020). "As TNF-a and IL-6 are known to induce insulin resistance, stimulate androgen production and disrupt the hypothalamic-pituitary-ovarian axis, the increased number of lymphocytes could be an factor triggering chronic inflammation and altered hormone secretion." (PMID 32103756, 2020). "This study allowed one to conclude that the inactive and sedentary lifestyle of female adolescents, along with excess body fat, insulin resistance, and higher concentrations of high-sensitivity C-reactive protein are associated to the higher concentration of TNF-α, IL-6, and leptin." (PMID 32694929, 2020). "Moreover, sleep deprivation over time during Ramadan leads to elevation of inducing proinflammatory cytokines, such as IL-6 which will decrease the level of adiponectin and exert insulin resistance." (PMID 32775407, 2020). "In addition, we observed that both senolytics induced a non-significant but evident reduction in the mRNA expression of the SASP factors Il6, Tnf and Il1b, proposed as mediators of insulin resistance." (PMID 32584785, 2020). "Thus, IL-6- or TNF-α-dependent insulin resistance is mediated, at least in part, by the induction of SOCS proteins in insulin target cells." (PMID 33255404, 2020). "In the long term, regular exercise, given the acute inflammatory response to exercise partly mediated by IL-6 may protect from low-grade inflammation and thus against insulin resistance." (PMID 33172413, 2020). "Moreover, high adiposity in neonates is related to insulin resistance, hyperinsulinemia, and a pro-inflammatory status characterized by high circulating levels of leptin and interleukin-6 (IL-6)." (PMID 33374585, 2020).
Insulin resistance (continued). "Moreover, available evidence has found that insulin resistance in COPD patients is associated with inflammation mediators such as C-reactive protein (CRP), interleukin-6 (IL-6) and tumour necrosis factor–α." (PMID 32393205, 2020). "Importantly, IL-6/STAT3 signaling was shown to regulate the depressive behavior as well as the process of insulin resistance." (PMID 32655424, 2020). "Animal studies confirm that A2BR activation increases serum IL-6 levels, which may be involved in the development of insulin resistance and improve insulin sensitivity." (PMID 32984382, 2020). "In this regard, some studies have suggested that increased TNF-α concentrations may impair the translocation of GLUT4 receptors, while IL-6 may have pro-inflammatory properties that lead to insulin resistance." (PMID 32187268, 2020). "Additionally, IL-6 levels, which have previously been reported to promote insulin resistance, were higher in obese IR than IS individuals." (PMID 33349270, 2020). "Although, IL-1, TNF-α, MIF, and IL-6 have consistently been shown to cause insulin resistance in WAT, their effects have not been extensively explored in BAT at the molecular level." (PMID 32265845, 2020). "In contrast, high adrenomedullin levels stimulated interleukin-6 and remarkably potentiated stimulatory effects of tumor necrosis factor-α, interleukin-1β and lipopolysaccharide that contribute to the development of insulin resistance." (PMID 33066780, 2020). "Moreover, the percentages of naïve CD4+ and CD8+ T cells were significantly higher, whereas activated T cells and IL-6 levels were lower in IS compared to insulin resistant (IR) obese individuals." (PMID 33349270, 2020). "The role of TNF-α and IL-6 in insulin resistance has remained controversial." (PMID 33066473, 2020). "Increased postprandial GIP secretion positively correlates with insulin resistance, and chronic local and systemic inflammation, which may involve IL-6 signaling." (PMID 32069846, 2020). "The decline of IL-10 and elevation of TNF-α and IL-6 are reported to be important regulators underlying insulin resistance and a slow nonhealing chronic wound process." (PMID 32879654, 2020). "In line with previous reports, we also identified a positive association of systemic IL-6 levels with insulin resistance, whereas other cytokines (IL-1ß, TNF, IL-10) did not correlate significantly." (PMID 33349270, 2020). "In addition, growing evidence reveals that dyslipidaemia is associated with increased levels of certain inflammatory mediators, including TNF-α and IL-6, which play a critical role in producing insulin resistance." (PMID 33322742, 2020). "Additionally, in hypertensive patients with cerebral infarction, inflammation (hs-CRP and IL-6 levels) and insulin resistance by homeostatic model assessment insulin resistance (HOMA-IR) index were associated with the diameter of the cerebral infarct." (PMID 33375333, 2020). "IL6 is an inflammatory cytokine involved in the development of insulin resistance." (PMID 32785109, 2020). "Also, out of 28 patients with chronic olanzapine consumption (unspecified dose) 14 were insulin-resistant and had a higher concentration of TNF-α, IL-6, IL-1β, and IL-8 with a positive correlation between these values and insulin resistance." (PMID 32373066, 2020). "Regarding blood tests, the fact that IL-6 and insulin were significantly higher in the high-salt group may suggest insulin resistance." (PMID 33198295, 2020). "Low muscle glycogen levels were accompanied by increased IL-6 which could induce insulin resistance." (PMID 31952248, 2020). "Most studies in vitro and in mice suggest that adipose-derived IL-6 promotes hepatic insulin resistance and glucose intolerance, while some indicate that in certain contexts IL-6 signaling in WAT and liver may be protective against metabolic disease." (PMID 32158768, 2020).